APC (APC regulator of Wnt signaling pathway)
Diseases named in the same sentence as APC in open-access papers (continued):
Sharing a sentence is not in itself a finding about the gene and the disease.
cancer (continued). "F-Box Protein 5 (FBXO5, also named Emi1) is a regulator of anaphase promoting complex/cyclosome (APC/C) activity in mitotic and meiotic cell cycle regulation and was reported to be overexpressed in a variety of cancer cells and enhance cancer progress." (PMID 39061113, 2024). "Interfering with APC/C substrate ubiquitylation in cancer cells delays mitotic exit, which induces cell death." (PMID 39595615, 2024). "To evaluate if these analyses were relevant in other contexts, we assessed global correlations of poly(A) site selection and APC gene expression in other cancer subtypes." (PMID 39375704, 2024). "β-catenin, a downstream molecule in the Wnt pathway, and two of its suppressors (APC and axin) are involved in cancer development." (PMID 38419887, 2024). "KIF18A-dependent cancer cells exhibit hallmarks of this SAC:APC/C imbalance, including a long metaphase-to-anaphase transition, and slow mitosis overall." (PMID 38279026, 2024). "In addition to APC mutations, a significant number of genetic alterations that induce β-catenin stabilization were identified in several components of the Wnt/β-catenin signaling cascade and are considered critical events in the development of different cancer types." (PMID 39065798, 2024). "Evidence from various reports has suggested the involvement of the APC gene in tumorigenesis of many cancer types, colorectal, gastric, and more." (PMID 39569232, 2024). "It is inevitable to turn a blind eye to the diagnostic value and the involvement of methylation status of APC promoter as a biomarker for cancer detection." (PMID 39569232, 2024). "A fraction of cancer cells are highly dependent on kinesin KIF18A function because of alterations in the ratio of APC/C and spindle assembly checkpoint (SAC) signals." (PMID 38279026, 2024). "The choice of surgical procedure is determined by various factors, including the genotype of adenomatous polyposis coli (APC), number of polyps, age, the presence of cancer, fertility, and quality of life." (PMID 38431759, 2024). "APC has been widely studied as a cancer suppressor, especially in sporadic colorectal cancer, in which hypermethylation of the CpG island in APC is considered one of the main pathogenic factors." (PMID 39794979, 2024). "The miR-135 family has been shown to indirectly influence the activity of the Wnt/β-Catenin signaling pathway by targeting APC, thereby promoting cancer progression." (PMID 39519092, 2024).
cancer (continued). "This identified role of APC as an RNA-binding protein has been largely unexplored in the context of cancer, and a link between APC and global regulation of 3′ UTR length is unreported in any context." (PMID 39375704, 2024). "In the context of CRC, deficiency in adenomatous polyposis coli (APC) results in TCF4/β-catenin-mediated upregulation of the TDO2-Kyn-AhR axis to increase glycolysis and drive anabolic cancer cell growth." (PMID 37876966, 2023). "CDC20 inhibitor Apcin has been reported to inhibit cancer cell proliferation by competitively inhibiting anaphase-promoting complex/Cyclosome (APC/C)-dependent ubiquitination." (PMID 36911196, 2023). "DNA was extracted from our initial 19 patient biopsies or organoids for genomic analysis of tumor suppressors and oncogenes using a QIAGEN Human Comprehensive Cancer Panel, which included APC." (PMID 37943618, 2023). "USP7 inhibitor treatment suppresses growth of patient-derived cancer organoids carrying APC truncations in vitro and in xenografts." (PMID 36669491, 2023). "Overall, we found that the loss of APC affects the activity of the ABC transporter, promoting cancer cells’ survival following DOX treatment." (PMID 37108784, 2023). "PVs in the APC gene were significantly more frequent in cancer patients than in the other groups and were observed at least twice as frequently in cancer patients than PVs in any other gene within the panel (p LLR = 0.0003)." (PMID 37306523, 2023). "Considering that appropriate downregulation of E2F1 is critical to maintaining genomic stability, blocking this process allows the inhibition of cancer cell growth, thus suggesting a critical role of APC/CCDH1 in DNA damage and cancer." (PMID 37176148, 2023). "Waszak and coworkers reported that all APC mutation carriers with available medical records (n=4) had a family history of FAP and associated cancers." (PMID 37746264, 2023). "Since APC/CCDH1 negatively regulates the level of PFKFB3 in cancer cells by ubiquitination, APC/CCDH1 plays a role in inhibiting cancer cell growth." (PMID 37176148, 2023). "Considering this, we have used in our studies SW480 cells and its metastatic derivative SW620 cell line for being cancer cells with truncated APC representing distinct stages of progression in the same patient." (PMID 36969011, 2023). "Tosyl-L-arginine methyl ester (TAME), an APC/C inhibitor, preferentially inhibits APC/C-Cdc20 instead of APC/C-Cdh1 to inhibit mitosis in cancer cells." (PMID 36526897, 2023). "The Adenomatous Polyposis Coli (APC) protein is an IDP that plays a key role in Wnt signaling and mutations in Apc initiate cancer." (PMID 37047451, 2023). "Apart from PVs of medium-high penetrance (MHPVs) in BRCA1/2, testing also includes low-penetrance alleles, which have been frequently reported in patients with cancer, for example, APC c.3920T>A and CHEK2 c.1283C>T." (PMID 38201524, 2023). "Suspecting FAP1, analyses of NGS for a cancer-associated genes panel and specific MLPA for the APC gene were requested." (PMID 37510409, 2023). "Recent reports suggest that knocking down fructose metabolism by deleting KHK suppresses cancer growth in response to HFCS in APC mice." (PMID 37559908, 2023).
cancer (continued). "We also found that other known cancer-related genes were also altered at low frequency including APC (n = 5), KRAS (n = 2), SETD2 (n = 2), DAXX (n = 1) and STAG2 (n = 1)." (PMID 37524847, 2023). "By the way, an average proportion of GAs for known oncogenes (e.g., KIT, MYC, CTNNB1, MDM2 and APC) in the same pan-cancer cohort ranges from four to 9%." (PMID 37373333, 2023). "Approximately 70% of CRCs follow the adenomatous polyposis coli (APC) pathway of development and are characterized morphologically by the classic progression of normal epithelial tissue to adenoma to carcinoma." (PMID 37569406, 2023). "Identifying novel interactions of APC in the Wnt pathway will provide an opportunity to understand APC’s nuclear role better and ultimately identify potential cancer treatment targets." (PMID 36457029, 2022). "In the excess of dsDNA, APC remained inhibitory activity to telomerase, attenuating cancer cell proliferation." (PMID 37288004, 2022). "The expressed level of APC is also involved in the level of CD8+ T-cell infiltration, Tregs infiltration, and cancer-associated fibroblast infiltration." (PMID 35303016, 2022). "In a 3D model of collective cancer cell invasion, the APC‐dependent mRNAs RAB13 and NET1 accumulate at the front of leader cells in invasive cell strands." (PMID 35166036, 2022). "Further analysis of our data found that the correlation of APC expression with the pathological stages of most cancers is low, a finding that suggests that APC has persistent low expression in cancer progression." (PMID 35303016, 2022). "Many of these genes were transcription factors and several of them were known cancer genes (e.g., APC, BCL2, ERBB2, HRAS, TGFBR2)." (PMID 35008420, 2022). "Our research provides a comparative wholesale understanding of the carcinogenic effects of APC in various cancers, which will help anti-cancer research." (PMID 35303016, 2022). "The role of the APC/c complex in cancer development and progression has been reviewed by VanGendersen and colleagues." (PMID 36293188, 2022). "In the NAW group, 318/141,673 (0.2%) participants with cancer were carriers of I1307K APC while only 73/58,918 (0.1%) individuals in the control group carried it [OR 1.81 (95% CI 1.41–2.35), p < 0.001]." (PMID 36497357, 2022).
cancer (continued). "Percent genomic alterations in COAD revealed a mutation frequency of 63% in APC gene and 38% in KRAS, making it as expected a highly WNT-activated and KRAS-driven cancer." (PMID 35664781, 2022). "In fact, a variety of tumor suppressor genes such as p16, p21, p14, Rb, p19, and APC in human cancers are transcriptionally silenced by methylation of CpG dinucleotides." (PMID 35328043, 2022). "Next, to ensure the synthetic lethality observed between the APC mutation and statin treatment, was not an artefact of our in vitro cell culture models, an in vivo CRC cancer model was used that represented APC-mutant patient tumors." (PMID 35712511, 2022). "Overall, 249,532 individuals with any type of cancer underwent multigene panel testing (MGPT) with a cancer panel that included APC." (PMID 36497357, 2022). "In this study, we applied online databases, including The Cancer Genome Atlas (TCGA) and Gene Expression Omnibus (GEO), to make a pan-cancer analysis of APC." (PMID 35303016, 2022). "We conducted a gene correlation study, but the findings seemed to contradict the previous analysis results of the low expression of the APC gene in most cancers." (PMID 35303016, 2022). "We divided the cancer cases into high-expression and low-expression groups according to the expression levels of APC and investigated the correlation between LAGE3 expression and the prognosis of LIHC patients with the help of TCGA datasets." (PMID 35313850, 2022). "Since genes often have different expression levels in different pathological stages, we used the GEPIA 2 online tool to analyze the correlation between APC gene expression and pathological stages of cancer." (PMID 35303016, 2022). "Mutations and alterations in adenomatous polyposis coli protein (APC) and/or Axin are observed in a range of cancer types highlighting the deregulation of the WNT pathway." (PMID 36359888, 2022). "The adenomatous polyposis coli (APC)/β-catenin/T-cell factor (TCF) pathway plays a significant role in the initiation of CRC cancer." (PMID 35885529, 2022). "Although APC I1307K is rare in NAW compared to AJ, it is indeed a moderate cancer risk allele for some cancer types, in addition to CRC." (PMID 36497357, 2022). "METTL3 was demonstrated to induce aerobic glycolysis by regulating the expression of adenomatous polyposis coli (APC) or HIF-1α in various cancers." (PMID 35757505, 2022). "β-catenin and adenomatosis polyposis coli (APC) are two key players in this pathway that play an oncogenic or tumor-suppressing role in various cancer types, including HCC." (PMID 33917049, 2021).
cancer (continued). "The analyses of TMG regulatory network based on multi-omics data above suggest some TMGs such as APC have suppressive effects on cancer immunity while some TMGs such as BARF play opposite roles." (PMID 34211853, 2021). "Variants with potential clinical significance were also identified in another 27 cancer genes, such as APC." (PMID 34640513, 2021). "The core component genes of the pathway CTNNB1, encoding for β catenin, APC and CDH1, encoding for E cadherin, are less frequently mutated, but also their prevalence is higher in PIK3CA mutated cancers than wild-type ones." (PMID 33435133, 2021). "Two genes—KRAS proto-oncogene, GTPase homolog (KRAS) (1.46%) and adenoma polyposis coli regulator of WNT signaling pathway (APC) (1.60%) contribute the most cancer predictions." (PMID 34032581, 2021). "In total, 29 germline pathogenic/likely pathogenic variants were identified in autosomal dominant cancer predisposition genes where the gene was pertinent to the cancer family history (including BRCA1/BRCA2, the mismatch-repair genes and APC)." (PMID 33654310, 2021). "Genetic mutations are well known to induce functional abnormalities of cancer-associated proteins, such as EGFR, KRAS and APC, resulting in cancer progression." (PMID 34202873, 2021). "The epitranscriptomic regulation of adenomatous polyposis coli (APC) tumour suppressor gene in cancers is unclear." (PMID 34155197, 2021). "To date, many genetic analyses using mice have confirmed the critical importance of APC in cancer development in the intestine." (PMID 33597597, 2021). "A major benefit of NIR-PIT is that only APC-bound cancer cells that are exposed to NIR light are killed by NIR-PIT; thus, minimal damage occurs in adjacent normal cells." (PMID 34064074, 2021). "The relationship between cancer and hypermethylation in APC CpG islands, however, has been shown to differ from cancer to cancer." (PMID 33968756, 2021). "We utilized the APC status-related drug responses from the Genomics of Drug Sensitivity in Cancer (GDSC)." (PMID 34440086, 2021). "Kaiso knockout leads to the delayed formation of smaller tumors in the intestine in APC min/− cancer model systems." (PMID 34299205, 2021). "APC is a negative regulator of Wnt/β-catenin signaling, which promotes the transcriptional activation of oncogenes in cancers." (PMID 33968785, 2021). "An examination of publicly available (TCGA) human RNA-seq data, CNA, and methylation revealed that NF2 and TAOK1 are deleted and under-expressed, the GDI2 promoter is hypermethylated, and APC is lost in a subset of human cancers." (PMID 33808166, 2021). "Activation of WNT signaling and enhanced cell migration are expected, since APC is one of the most frequent mutated genes in CRC and cell migration is a hallmark for cancer cells." (PMID 34737287, 2021). "Using patient-derived cancer organoid and an APC-MIN mice model, we found the combinatory approach to be effective for APC-mutated CRC." (PMID 34298652, 2021).